IL10 (interleukin 10)
Diseases named in the same sentence as IL10 in open-access papers (continued):
Sharing a sentence is not in itself a finding about the gene and the disease.
Cognitive impairment (97 papers, 2010 to 2026). Abnormal cognition is characterized by deficits in thinking, reasoning, or remembering. "Key findings indicate that elevated levels of inflammatory markers such as IL‐6, IL‐1β, and sTNFRs are linked to cognitive impairment and neurodegeneration, while the role of IL‐10 and IL‐8 present varying associations based on demographic factors." (PMID 40709483, 2025). "Interleukin (IL)‐10 plays a notable role in the inflammatory‐associated mild cognitive impairment (MCI)." (PMID 37532673, 2023). "Particularly, an “A” allele at position 1082 has been associated with low production of IL-10 and is implicated in promoting mild cognitive impairment (MCI) to AD." (PMID 34275478, 2021). "Few studies have linked the role of IL-10 with cognitive deficits in schizophrenia." (PMID 35887634, 2022). "Furthermore, IL-10, a major anti-inflammatory cytokine, exacerbates amyloid-β plaque burden and cognitive impairment, whereas IL-10 deficiency enhanced amyloid-β clearance in Alzheimer’s disease model mice." (PMID 33931083, 2021). "Altogether our findings show that IL-10 provides pro-cognitive actions in learned helpless mice or mice with cognitive impairments possibly associated with microglial dysfunction affecting synapse balance, opening potential new therapeutic avenues to correct learning and memory deficits." (PMID 32828124, 2020). "The diverse role of cytokines in the progression of AD-like pathology is underscored by recent observations showing that overexpression of the anti-inflammatory cytokine IL-10 negatively affected cognitive function, whereas IL-10 deficiency significantly restored cognitive impairment of APPPS1 mice." (PMID 28646899, 2017). "In the present study, we report the results of the first formal examination, to our knowledge, of whether IL-10 and IL-18 promoter SNPs are associated with cognitive impairment in PD." (PMID 26830320, 2016). "In their study, the authors have analysed genotype and allele frequencies of A allele of −1082 polymorphism (G/A) of interleukin-10 (IL-10) in 138 subjects with mild cognitive impairment (MCI) diagnosed respectively as amnestic (a-MCI) and multiple impaired cognitive domains (mcd-MCI)." (PMID 20871836, 2010). "In the healthy human brain, the IL10 gene and its receptors are involved in the regulation of neuroinflammation and synaptic functions that are important for cognition, and hence their deficiency may contribute to cognitive impairment in SCZ." (PMID 37510364, 2023). "The interleukin 10 (IL-10) allele could contribute to cognitive impairments in schizophrenia." (PMID 35163141, 2022). "Administration of IL-10 ameliorates stress-induced cognitive deficits and improves recognition and spatial memory in experimental animals." (PMID 40076857, 2025). "Of note, there were also elevated levels of IL-10, IFNγ, and sTREM2 in long-COVID patients, especially in the group suffering from cognitive impairment." (PMID 39799217, 2025). "In contrast, the anti-inflammatory genes, such as IL-10 and CD30, were significantly decreased in these mice, demonstrating that ethanol-induced cognitive impairment is related to immune deficiency and inflammatory response." (PMID 40666518, 2025). "Such a study showed also a correlation between serum IL-10 levels and the severity of tremor and higher serum IL-6 levels in patients with ET and cognitive impairment." (PMID 39769168, 2024). "This is surprising as postsurgical studies in elderly patients found plasma TNFα, IL-6, and IL-10 levels to be independent predictors for adverse central postoperative outcomes such as cognitive deficits." (PMID 38585987, 2024). "Fish oil intake improved depressive-likesymptoms and cognitive impairment, reduced proinflammatory cytokineexpression, activated the brain’s glial cells, and increasedthe interleukin-10 level in the prefrontal cortex." (PMID 37769277, 2023).
Cognitive impairment (continued). "Several studies reported that reductions in IL-4 and IL-10 production markedly worsened cognitive impairment in AD patients and in the hippocampus of the Aβ1–42-injected rat model." (PMID 36359200, 2022). "Short-term (i.e., 10-24 weeks) moderate- to high-intensity strength training reduced LPS–IL-6, LPS, IL-1β, LPS–TNF-α and circulating concentrations of TNF-α and increased IL-10 in healthy elderly women and older people with cognitive impairment, respectively." (PMID 33936044, 2021). "After adjustment for age and sex, PD-cognitive deficit was positively associated with plasma EV pro-IL-1β, IL-6, TNF-α, and IL-10 levels and negatively with the TGF-β1 level." (PMID 33803292, 2021). "Correlations were found between IL-6, IL-8, and IL-10 levels and some clinical parameters, especially the severity of cognitive impairment." (PMID 33362607, 2020). "They examined the cross-sectional and longitudinal associations between baseline-measured IL-6, IL-10, and tumor necrosis factor (TNFα) levels in the blood and the ratio of IL-6/IL-10 with cognitive test performance and mild cognitive impairment." (PMID 32455758, 2020). "IL-10 has some behavioral effects arising from pro-inflammatory cytokines inhibition, showing its potential to ameliorate neuroinflammation, cognitive deficits and neurodegeneration." (PMID 27142962, 2016). "On the other hand, the attenuation of neurodegeneration by IL-10 was supported by AD studies in transgenic mouse models, in which IL-10 could reduce neuroinflammation, promoting neurogenesis and improving spatial cognitive deficits." (PMID 39891777, 2025). "In drug-naive first-episode SZ subjects, a significant decrease in IL-10 was observed, and there was an inverse correlation with negative symptoms from the PANSS scale, which could suggest a possible relation between IL-10 decrease and cognitive impairment." (PMID 39796167, 2025). "In addition, L. gasseri NK109 showed a protective effect that alleviated neuroinflammation and cognitive impairment by decreasing the expression of IL-1β and increasing the expression of the anti-inflammatory cytokine IL-10." (PMID 40002326, 2025). "In addition, IL-10, as an anti-inflammatory factor, has been observed to be involved in the protective effect of methane on cognitive impairments in a mouse model of POCD." (PMID 38912522, 2024). "Another study revealed that the copresence of elevated blood TNF-α/IL-10 levels and mild cognitive impairment could predict early conversion of idiopathic rapid-eye-movement sleep behavior disorders into neurodegenerative synucleinopathies." (PMID 36897204, 2023). "Our analysis revealed that, in patients with cognitive impairment due to AD, (i) sPECAM-1, sP-, sE-Selectins, and IL6 were associated with amyloid and tau pathology; (ii) sP-Selectin, sNCAM, and the decrease of IL10 with neurodegeneration; and (iii) LPS and IL1β with cognitive impairment." (PMID 37254223, 2023). "It is generally acknowledged that neuroinflammation plays an important role in the pathogenesis of Alzheimer’s disease and there are more inflammatory markers (TNFα, IL-1β, IL-6, IL-10) in patients with AD and mild cognitive impairment (MCI) than in healthy controls." (PMID 37081917, 2023). "However, LPS treatment suppressed IL-10 expression and the Bacteroidaceae population, which were negatively correlated with cognitive impairment-like behaviors." (PMID 34579150, 2021). "We also tested if IL-10 treatment ameliorated cognitive impairments in female wild-type mice." (PMID 32828124, 2020). "Since in LH mice microglial activation was reduced by treatment with IL-10 and microglial cells contributed to the impaired learning and memory in LH mice, we tested if IL-10 administration reverses cognitive impairments in LH mice." (PMID 32828124, 2020).
Cognitive impairment (continued). "Furthermore, carnosine showed the ability to rescue IL-10 levels, an anti-inflammatory cytokine whose deficit in AD patients seems to play a key role in promoting neuroinflammation and cognitive deficits." (PMID 30658430, 2019). "IL-10 levels did not correlate with tau biomarkers, but were associated with rates of longitudinal cognitive decline in mild cognitive impairment due to AD (p = 0.006)." (PMID 30253800, 2018). "Also, a recent study demonstrated an increased production of IL-6 and IL-10 in mild cognitive impairment suggesting that immune activation is an early phenomenon that precedes AD." (PMID 22428008, 2012). "Increased pro-inflammatory cytokines levels (TNFα, Interleukin-6, Interleukin-1β), combined with decreased levels of anti-inflammatory cytokines (Interleukin-10), have been correlated with cognitive deficits suggesting that early inflammatory changes may be detrimental." (PMID 22838967, 2012). "AYAC both during and post-chemotherapy had higher rates of self-perceived and objective cognitive impairment, lower plasma BDNF, and elevated IL-4, IL-6, IL-8, IL-10, and IFN-γ compared to NC during follow-up." (PMID 40597835, 2025). "Worsening cognitive impairment was correlated with a decrease in the cytokines IFN-γ, IL-1β, IL-2, IL-4, and IL-10." (PMID 37569491, 2023). "In this study, we found that PBMT treatment of APP/PS1 and 3xTg-AD mice lymph nodes promoted AHN to improve cognitive deficits, these effects mainly due to the upregulation of IFN-γ/IL-10 protein expression in brain tissue after PBMT treatment." (PMID 36217178, 2022). "High levels of interleukin-10 (IL-10), interleukin-1 (IL-1), Tumor Necrosis Factor (TNF)-alpha have been observed in patients with cognitive impairment." (PMID 35889934, 2022). "Many BafA1- or Rapa-induced up-regulated pro-inflammatory cytokines (e.g., IL-1B, TNFs, IL10, IL12, and IL13), correspond to the presence of CNS pathologies like cognitive impairment observed in patients with meningitis." (PMID 32225060, 2020). "For example, knock out of interleukin-10 (IL-10), an anti-inflammatory cytokine, ameliorated cognitive impairment in APP/PS1 mice, consistent with enhanced IL-10 signaling in AD brains." (PMID 26074767, 2015). "In fact, recent data from our laboratory have shown that nephrectomy-induced cognitive impairment in rats seems to be related to an increase in GCs levels in cerebrospinal fluid (CSF) and TNF-α/IL-10 ratio compared to the Sham group." (PMID 26647069, 2015). "Although HFFD did not lead to cognitive impairment in the present study, DI values were positively correlated with brain IL‐10 and negatively correlated with plasma CD36 and IL‐6." (PMID 39619979, 2024). "Nevertheless, cognitive impairment was not correlated to IL-6, IL-8, or IL-10 at any time point (all P>0.05)." (PMID 37878890, 2023). "Blood studies showed that higher levels of pro-inflammatory markers were linked with a more severe motor phenotype (IFN-γ, TNF-α, IL-2, and IL-10), faster motor progression (CRP and IL-6), cognitive impairment (IFN-γ, TNF-α, IL-2, and IL-10), and worse sleep quality (CRP)." (PMID 36337703, 2022). "Despite IL-10 being known to inhibit pro-inflammatory cytokines, an increase in IL10 expression in several animal models of AD provoked a decrease in Aβ phagocytosis by microglia and exacerbated Aβ deposits, leading to cognitive impairment." (PMID 33918172, 2021). "However, oral administration of NK210, NK219, or Mx decreased cognitive impairment-like behaviors, NF-κB+/Iba1+ cell population, and IFN-γ and TNF-α expression in the hippocampus, while BDNF+/NeuN+ cell population and IL-10 expression increased." (PMID 34667205, 2021). "However, oral administration of NK210, NK219, or Mx decreased cognitive impairment-like behaviors, NF-κB+/Iba1+ cell population, and TNF-α and IFN-γ expression in the hippocampus, while BDNF+/NeuN+ cell population and IL-10 expression increased." (PMID 34667205, 2021).
Cognitive impairment (continued). "Furthermore, strength training lasting 28 weeks increased IL-10 levels and slight maintained TNF-α levels in older women with cognitive impairment." (PMID 33936044, 2021). "Finally, patients with PD and cognitive deficit (MMSE < 26) (n = 51) exhibited significantly increased plasma EV pro-IL-1β, IL-6, TNF-α, and IL-10 levels and a significantly decreased TGF-β1 level." (PMID 33803292, 2021). "Seven variables were identified as key predictors of cognitive impairment, including age, years of education, septic shock, benzodiazepine use, acute physiology and chronic health evaluation II (APACHE II) score, sequential organ failure assessment (SOFA) score, and interleukin-10 (IL-10) level." (PMID 41647020, 2026). "In conclusion, NK210, Lactobacillus sp, and NK219, Bifidobacterium additively or synergistically control IFN-γ to IL-10 and TNF-α to IL-10 expression ratios in the host with and without immune imbalance, resulting in the alleviation of gut dysbiosis, inflammation, and cognitive impairment." (PMID 34667205, 2021). "Therefore, the diminished IL-10, in combination with increased IL-1β, that we observed in DEP/NR males could affect their relative vulnerability to cognitive impairments and mood dysregulation, compared with DEP/​NR females, which did not exhibit such a proinflammatory bias." (PMID 23823752, 2013). "Importantly, the role of the anti-inflammatory cytokine IL-10 in AD brain remains controversial, since recent studies in APP mice suggested that it may inhibit microglial Aβ clearance, promoting Aβ plaque generation and cognitive impairment (rather than delaying AD progression)." (PMID 32143329, 2020).
lymphopenia (96 papers, 2011 to 2026). Reduction in the number of lymphocytes. "A sustained inflammatory response driven by a ‘cytokine storm’, including the release of pro-inflammatory cytokines (TNF-α, IL-6, IL-8 and IL-10) and lymphopenia, is thought to be a major cause of life-threatening complications in SARS-CoV-2 patients." (PMID 36313994, 2022). "Alternatively, virus can trigger inflammatory response in the form of SIRS, lymphopenia, macrophage activation and cytokine storm releasing IL-6, IL-10 and TNF-α which can cause myocarditis." (PMID 33615872, 2021). "In the present study, we reported that lymphopenia caused by FMDV was associated with the disease severity, and IL-10 was related to the occurrence of lymphopenia caused by FMDV infection." (PMID 34960627, 2021). "Overall, these results from the IL-10-/- mice further indicated that IL-10 plays an important role in lymphopenia caused by FMDV infection." (PMID 34960627, 2021). "IFN-γ activation and cytokine responses (mainly IL-6 and IL-10) may cause a cytokine storm in some patients with a more severe acute phase of disease and lymphopenia and multisystemic organ involvement." (PMID 36263058, 2022). "Type II IFN activation and cytokine responses (mainly IL-6 and IL-10) may cause a cytokine storm in some patients with a more severe acute phase of the disease, lymphopenia and multisystemic organ involvement." (PMID 36263058, 2022). "At a dose of 100 μg/kg, IL-10 can cause several side effects, including mild-to-moderate flu-like symptoms (fever with chills, headache, fatigue, myalgias, gastrointestinal disturbances, transient lymphopenia, transient thrombocytopenia, elevated transaminase levels, and injection site reactions." (PMID 38248028, 2024). "However, it is still unclear if IL-10 is involved in lymphopenia caused by FMDV infection." (PMID 34960627, 2021). "Foot-and-mouth disease virus (FMDV) infection elicits sustained, high-level interleukin-10 (IL-10) secretion in cattle and pigs, which correlates with lymphopenia and immunosuppression." (PMID 41600831, 2026). "In a humanized NSG mice model, treatment with the CAR-Treg led to increased levels of IL-10, decreased positivity of anti-dsDNA, delayed the onset of lymphopenia and decreased inflammation in lung, spleen and kidney biopsies." (PMID 40481370, 2025). "Blocking IL-10/IL-10R signaling using in vivo anti-mouse IL-10R (clone 1B1.3A) was able to prevent lymphopenia, which contributes to enhancing the survival of mice infected with FMDV." (PMID 41156600, 2025). "Loss of Hem1 resulted in hallmarks of T cell exhaustion, including T cell lymphopenia, decreased activation and proliferation, increased expression of PD-1 and Tim3, and increased IL-10 production." (PMID 40627451, 2025). "Recent studies using IL-10 knockout mice have shown that blocking the IL-10 signaling pathway can prevent lymphopenia by reducing apoptosis and altering lymphocyte trafficking and co-inhibitory expression, thereby enhancing survival in FMDV-infected mice." (PMID 39340101, 2024). "IL-6, IL-10, and TNF-α seem to correlate with lymphopenia, while convalescent patients showed lower IL-6 and IL-10 levels, respectively." (PMID 36034704, 2022). "Muscle-derived IL-6, one of the myokines with anti-inflammatory properties, inhibits TNF production and stimulates the production of IL-1ra and IL-10 as well as cortisol production, leading to lymphopenia and neutrocytosis." (PMID 36077525, 2022). "After serial administration of high doses of IL-10, clinical complications were observed such as neutrophilia, monocytosis, and lymphopenia." (PMID 35270791, 2022). "Similar to observations from septic patients, lymphopenia in mice affected different subsets heterogeneously and there was actually an increase in the proportion of IL-10-producing regulatory B cells." (PMID 33021569, 2021).